SNORA73 (Small nucleolar RNA SNORA73 family )
Synonyms: LOC124904363
Gene: Small nucleolar RNA gene on chromosome 18 (56,079,394 to 56,079,594, reverse strand). Ensembl gene ENSG00000201816.
Gene Ontology:
Biological process: RNA processing
Cellular component: nucleolus
Homologues: Orthologues: chimpanzee SNORA73 (99% identical), macaque SNORA73 (93% identical), rabbit SNORA73 (82% identical), rabbit SNORA73 (81% identical), rabbit SNORA73 (80% identical), guinea pig SNORA73 (79% identical), rabbit SNORA73 (79% identical), rabbit SNORA73 (66% identical). Paralogues in human: SNORA73B (86% identical), SNORA73A (82% identical), RNU105B (79% identical), SNORA73 (79% identical), RNU105C (78% identical), SNORA73 (69% identical), SNORA73 (37% identical).
Diseases named in the same sentence as SNORA73 in open-access papers:
SNORA73 is named in the same sentence as 4 diseases in open-access papers, as found by Europe PMC text mining. Sharing a sentence is not in itself a finding about the gene and the disease. The quoted sentences say what the papers report.
psoriasis (2 papers, 2024 to 2025). An autoimmune condition characterized by red, well-delineated plaques with silvery scales that are usually on the extensor surfaces and scalp. "In recent years, exploring novel treatment avenues such as targeting IL-21, small nucleolar RNA (snoRNA) Snora73, the gut microbiome, and natural remedies have shown increasing promise in managing psoriasis." (PMID 40161116, 2025). "Identifying Snora73 as a crucial regulator in the expression factors involved in psoriasis pathology offers a promising new avenue of therapeutic intervention." (PMID 40161116, 2025). "Evidence has shown increased levels of Snora73 in psoriasis patients, where psoriasis cells demonstrated increased viability and migration." (PMID 40161116, 2025). "Collectively, these findings reveal a crucial role of Snora73 in progression of psoriasis through miR-3074-5p/PBX1 signaling pathway and suggest a potential therapeutic strategy." (PMID 38240925, 2024). "And then, the expression of top 10 candidate snoRNAs was validated in psoriasis tissues and psoriasis plasma using qPCR; we observed that Snora73 was most upregulated in psoriasis tissues samples and plasma samples compared their normal control." (PMID 38240925, 2024). "These indicated that miR-3074-5p reversed the Snora73 ability of boosting the psoriasis advancement." (PMID 38240925, 2024). "Firstly, we screened the snoRNAs from five matched pairs of psoriasis and normal tissues using small RNA microarray assays and identified a novel and highly expressed Snora73 in psoriasis." (PMID 38240925, 2024). "Overexpression of Snora73 significantly increased psoriasis cells viability and migration, while knockdown of Snora73 got the opposite results." (PMID 38240925, 2024). "We also showed that Snora73 was most highly expressed not only in psoriasis plasma but also in psoriatic lesions." (PMID 38240925, 2024). "In this paper, we found high expression of Snora73 in psoriasis and serving as a sponge of miR-3074-5p." (PMID 38240925, 2024). "In summary, we demonstrated that Snora73 was highly expressed in psoriasis, and Snora73 promoted the progression of psoriasis." (PMID 38240925, 2024). "Targeting IL-21, Snora73, and the gut microbiome, as well as utilizing natural treatments, may provide new opportunities for more effective, personalized management of psoriasis." (PMID 40161116, 2025). "A specific snoRNA, Snora73, was highly expressed in psoriasis and further promotes its progression." (PMID 40161116, 2025). "Secondly, the role of Snora73 in psoriasis pathology was studied." (PMID 38240925, 2024). "The limitation of the study is whether or how the effect of Snora73 in psoriasis progression in Snora73 knockdown mice model." (PMID 38240925, 2024). "The results showed that a new snoRNA Snora73 was upregulated in psoriasis patient samples." (PMID 38240925, 2024). "We observed that Snora73 knockdown could obviously suppress psoriasis cell proliferation and migration, while the Snora73 overexpression exerted opposing effects." (PMID 38240925, 2024). "These outcomes showed that Snora73 promotes the progression of psoriasis." (PMID 38240925, 2024). "In addition to IL-21, snoRNA Snora73 has emerged as a novel target for psoriasis treatment." (PMID 40161116, 2025). "Furthermore, snoRNA Snora73 has also been shown to play a role in the pathogenesis of psoriasis." (PMID 40161116, 2025). "Snora73 regulates cell proliferation by interacting with miR-3074-5p and pre-B-cell leukemia homeobox 1 (PBX1), promoting abnormal cell turnover in psoriasis." (PMID 40161116, 2025). "Mechanistically, our results showed that Snora73 acted as a sponge for miR-3074-5p and PBX1 is a direct target of miR-3074-5p in psoriasis cells." (PMID 38240925, 2024). "However, the biological role of Snora73 in psoriasis cell dysfunction remains unclear." (PMID 38240925, 2024).
psoriasis (continued). "By targeting the binding of Snora73 with miR-3074-5p, excessive production of PBX-1 may be reduced, curbing the erratic keratinocyte proliferation notable in psoriasis." (PMID 40161116, 2025). "Importantly, we found that Snora73 acted as a sponge for miR-3074-5p and PBX1 is a direct target of miR-3074-5p in psoriasis cells." (PMID 38240925, 2024).
acute myeloid leukemia (1 paper, 2024). Acute myeloid leukemia (AML) is a group of neoplasms arising from precursor cells committed to the myeloid cell-line differentiation. "The inhibition of SNORA73 expression reduces the levels of DNA damage in acute myeloid leukemia (AML) cells while enhancing genome stability." (PMID 39118131, 2024).
Hepatic steatosis (1 paper, 2021). Steatosis is a term used to denote lipid accumulation within hepatocytes. "Furthermore, we show that knockdown of SNORA73 in vivo protects against hepatic steatosis and lipid-induced oxidative stress and inflammation." (PMID 34471131, 2021).
steatosis (1 paper, 2021). Increased lipid within the cytoplasm of cells. "Our studies show that selective knockdown of SNORA73 in mice confers protection from HFD-induced steatosis, and from steatosis, inflammation, and oxidative stress induced by the MCD diet." (PMID 34471131, 2021). "The observations that knockdown of SNORA73 in vivo reduced steatosis and markers of tissue damage are consistent with a model in which depletion of SNORA73 protects against lipotoxicity." (PMID 34471131, 2021).